CCND1 (cyclin D1)
Diseases named in the same sentence as CCND1 in open-access papers (continued):
Sharing a sentence is not in itself a finding about the gene and the disease.
squamous cell carcinoma (51 papers, 2006 to 2025). A carcinoma arising from squamous epithelial cells. "The increase in growth of A431 human epidermoid carcinoma (CRL-2592) cells treated with CsA was associated with enhancement of the expression of CYCLIN D1 protein." (PMID 39705288, 2024). "The infiltrative tumor cells in CIN 3-like squamous cell carcinomas of the uterine cervix showed a nuclear expression of cyclin D1 and loss of e-cadherin whereas the central parts of the tumor demonstrated a reverse staining pattern." (PMID 34495397, 2022). "al reported increased cytoplasmic cyclin D1 expression to be associated with advanced tumor stage and presence of invasive cell morphology in squamous cell carcinomas, and in addition an association between nuclear and cytoplasmic expression." (PMID 35637257, 2022). "Several reports from different parts of the world have been published with reference to CCND1 polymorphism and risk of various types of cancers including cervical, prostate, colorectal, urinary bladder, squamous cell carcinoma of the head and neck etc.." (PMID 30361291, 2018). "Additionally, the proliferation of A431 human epidermoid carcinoma (CRL-2592) cells has been linked to elevated levels of the CYCLIN D1 protein." (PMID 39727652, 2024). "Cyclin D1 levels are typically under stringent regulation, but aberrant cyclin D1 expression has been implicated as having oncogenic properties in many neoplasias including breast, pituitary, and squamous cell carcinoma." (PMID 17375037, 2007). "Squamous cell carcinomas showed frequent genic amplification of CCND1 and SOX2 and/or TP63, while ERBB2, VEGFA, GATA4, and GATA6 were more commonly amplified in adenocarcinomas." (PMID 37893095, 2023). "Squamous cell carcinomas showed frequent genomic amplifications of CCND1 and SOX2 and/or TP63, whereas ERBB2, VEGFA and GATA4 and GATA6 were more commonly amplified in adenocarcinomas." (PMID 28052061, 2017). "Cyclin D1 performs a critical cell cycle regulatory function during G2 phase and silencing of Cyclin D1 also had an effect on apoptosis induction in several squamous cell carcinoma cell lines." (PMID 27491866, 2016). "In squamous cell carcinoma cell lines VAE treatment led to a substantial decrease in the expression level of Cyclin D1." (PMID 27491866, 2016). "In this study, we designed several sgRNAs targeting human cyclin D1 mRNA and examined the effects on squamous cell carcinoma (SCC) cells." (PMID 25437003, 2014). "Cyclin D1 overexpression has been reported in squamous cell carcinoma in a variety of head and neck subsites including the larynx, hypopharynx and tongue." (PMID 23672832, 2013). "Squamous cell carcinomas of the esophagus with chromosome 11q13 amplification indicated simultaneous CCND1 gene amplification." (PMID 23194200, 2012). "Labelling index values increased on progression from normal larynx through laryngeal dysplasia to squamous cell carcinoma for Mcm-2 (P=0.001), Ki67 (P=0.0002), cyclin D1 (P=0.015), cyclin A (P=0.0001) and cyclin B1 (P=0.0004)." (PMID 16832409, 2006). "Abnormalities in cyclin D1 are common in squamous cell carcinoma and adenocarcinoma." (PMID 32957082, 2020). "Similar to MYC, CCND1 is frequently amplified in the squamous cell carcinoma." (PMID 32405341, 2020). "CCND1 is a human oncogene involved in a number of cancers including squamous cell carcinomas." (PMID 25901368, 2015). "The tumor suppressive activity of SIP1 has been appreciated by several studies, in which SIP1 has been shown to induce G1 phase cell cycle arrest by inhibiting cyclin D1 expression in squamous carcinoma cells, or to repress hTERT expression, resulting in replicative senescence in HCC cells." (PMID 26378039, 2015).
squamous cell carcinoma (continued). "Also, induced expression of SIP1 has recently been shown to directly inhibit cyclin D1 in the A431 squamous carcinoma cell line, leading to the accumulation of cells in the G1 phase." (PMID 21645397, 2011). "Therefore, the present study was planned to study cyclin D1 expression in patients with tobacco-related intraoral squamous cell carcinoma and their correlation with clinicopathological features and aggressive DNA pattern as determined by DNA flow cytometry." (PMID 21537090, 2011). "Interestingly, in the case of stromal cells derived from a surgical tissue specimen of squamous cell cancer of oesophagus, the cyclin D1 expression in tumour stromal cells was downregulated as compared with that observed in normal stromal cells." (PMID 20407446, 2010). "Interestingly, it has been suggested that cyclin D3 preferentially promotes development of squamous carcinomas and that it activates an oncogenic pathway in mammary epithelial cells that is distinct from the pathway induced by cyclin D1." (PMID 16569260, 2006). "Also, inhibition of Nfκb in hepatocytes in a diethyl nitrosamine chemical model enhances cyclin D1 expression and cell proliferation, while blockade of Nfκb through overexpression of Iκbα promotes Ras-induced epidermal growth resembling squamous cell carcinoma." (PMID 23516545, 2013). "Also, by directly inhibiting cyclin D1, SIP1 caused G1 arrest in squamous carcinoma cells." (PMID 21645397, 2011). "Potential tumor suppressor genes, also found in other squamous cell carcinomas, have been discovered in the lost regions 2q33-q37.3 (PLCD4), 3p26.3-q11.1 (RBMS3, PLCD1, and CACNA2D3) and 11q12.2-q25 (CPT1A, CCND1, FGF4/FGF3, and PPP2R1B)." (PMID 26901676, 2016). "For example, AQP3 overexpression in AQP3-PC12 cells and epidermoid carcinoma cells (A431), which express high levels of AQP3, accelerates cell cycles, and treatment with the AQP3 inhibitor leads to arrest in the S-G2/M phases and enhances the expression of cyclin D1 and E1 proteins." (PMID 35252273, 2022). "However, cyclin D1 overexpression was found to be significantly associated with poor RFS in adenocarcinoma (P = 0.03), not in squamous cell carcinoma (P = 0.46)." (PMID 26681199, 2015).
head and neck squamous cell carcinoma (49 papers, 2006 to 2026). A squamous cell carcinoma that arises from any of the following anatomic sites: lip and oral cavity, nasal cavity, paranasal sinuses, pharynx, larynx, and salivary glands. "Gene expression profiling of the Head and Neck Squamous Cell Carcinoma (HNSC) project of The Cancer Genome Atlas (TCGA) program identified the TPRG1-AS1-hsa-miR-363-3P-MYO1B gene regulatory axis associated with CCND1." (PMID 37481637, 2023). "Between 30% to 83% of head and neck squamous cell carcinoma (HNSCC) were reported to be associated with cyclin D1 over-expression." (PMID 16953893, 2006). "Amplification of 11q13 (FGF3/4/19, CCND1) is frequently observed in head and neck squamous cell carcinoma (HNSCC)." (PMID 40974176, 2025). "In head and neck squamous cell carcinoma, the amplification and overexpression of CCND1 were related to poor prognosis." (PMID 37024471, 2023). "In head and neck Squamous cell carcinoma, CCND1 amplification is allied to the progression of heterogeneous proliferative lesions to carcinoma in situ and is associated with a unfavorable clinical outcome." (PMID 37481637, 2023). "Over-expression of cyclin D1 has been observed in many cancer types like head and neck squamous cell carcinomas (HNSCC), pancreatic and breast cancer." (PMID 33557101, 2021). "In head and neck squamous cell carcinoma (HNSCC), it is often associated with the overexpression of cyclin D1 (CCND1)." (PMID 32224897, 2020). "An antisense cyclin D1 sequence in head and neck squamous cell carcinoma (HSNCC) cells inhibits cell growth, induces apoptosis and enhances sensitivity to chemotherapeutic agents both in vitro and in vivo." (PMID 32872659, 2020). "Altered CCND1 expression has been reported in many different cancers, including head and neck squamous cell carcinoma." (PMID 32224897, 2020). "Patients with head and neck squamous cell carcinomas (HNSCC) with high cyclin D1 tumor expressions were less likely to respond to neo-adjuvant cisplatin-based CHT and survive, than patients with low expressions of the marker (58 vs. 85%; p < 0.001)." (PMID 29332262, 2018). "Deletion of CDKN2A (p16) or amplification of CCND1 (cyclin D1) occurs commonly in head and neck squamous cell carcinoma (HNSCC) and induces sustained cyclin-dependent kinase (CDK) 4/6 activation." (PMID 26909611, 2016). "Altered cyclin D1 expression contributes to the progression of different tumors and participates in the invasion of head and neck squamous cell carcinoma." (PMID 25591548, 2015). "Cyclin D1 expression should be downregulated in HPV-positive head and neck squamous cell carcinoma as a result of pRb suppression." (PMID 23672832, 2013). "Wang and colleagues also reported that antisense CCND1 enhances the sensitivity of head and neck squamous cell carcinoma cells to cisplatin." (PMID 16978399, 2006). "To substantiate the prognostic significance of our model, we recruited a clinical cohort consisting of 20 patients with head and neck squamous cell carcinoma at various clinical stages to verify the expression of the four genes (CCND1, FTH1, YWHAG and TNFRSF12A)." (PMID 37882107, 2024). "Cyclin D1 is highly expressed in many human cancers including pancreatic adenocarcinoma, lung cancer, breast cancer, head and neck squamous cell carcinoma (HNSCC), cutaneous melanoma, endometrial cancer, colorectal carcinoma, ESCC, mantle cell lymphoma, and so forth." (PMID 35565262, 2022). "Head and neck squamous cell carcinoma (HNSCC) exhibits increased expression of cyclin D1 (CCND1)." (PMID 25437003, 2014). "In this study, we tested the hypothesis that CCND1 expression determines response and clinical outcomes in locally advanced head and neck squamous cell carcinoma (HNSCC) patients treated with neoadjuvant chemotherapy followed by surgery and radiotherapy." (PMID 22065993, 2011).
head and neck squamous cell carcinoma (continued). "For example, the expression level of cyclin D1 (CCND1) was shown to be significantly reduced in patients with head and neck squamous cell carcinoma (HNSCC) following nivolumab treatment." (PMID 38539545, 2024). "Amplification of proto-oncogene, cyclin D1, is another finding in head and neck squamous cell carcinoma (HNSCC)." (PMID 28855922, 2016). "In addition, ENO2 has been found to interact with PKM2, preventing PKM2 ubiquitin-mediated proteasomal degradation and regulating PKM2-driven CCND1-mediated cell cycle progression, proliferation, and glycolysis in head and neck squamous cell carcinoma (HNSCC)." (PMID 39061144, 2024). "Whereas, up-regulation of lincRNA-p21 resulted in G1 arrest in HN6 and Cal27 cells as well as reducing the expression levels of several cell cycle regulating factors such as Cyclin B1 and Cyclin D1 along with the apoptosis induction in head and neck squamous cell carcinoma (HNSCC) cells." (PMID 32582435, 2020). "The comprehensive genomic analysis of the head and neck squamous cell carcinoma (HNSCC) oncogenome revealed the frequent loss of p16INK4A (CDKN2A) and amplification of cyclin D1 genes in most human papillomavirus–negative HNSCC lesions." (PMID 38954773, 2024). "Moreover, Cyclin D1 and CDK4 downregulation through syntenin depletion was previously reported in head and neck squamous cell carcinoma." (PMID 26539120, 2015). "CCND1 is also frequently co-amplified with FGF19 in head and neck squamous cell carcinoma, amplification of which was seen in 18 (35%) of patients in our cohort—FGF19 is involved in HNSCC tumorigenesis and may be useful as a target for therapy." (PMID 39324009, 2024). "Honokiol, isolated from the bark, seed cones and leaves of the trees of the genus Magnolia, could inhibit EGFR in head and neck squamous cell carcinoma (HNSCC) cells, resulting in reduced activities of its downstream proliferative and survival targets, such as AKT, STAT3, BCL-XL and cyclin D1." (PMID 35269825, 2022).
renal cell carcinoma (39 papers, 1999 to 2025). "Based on genome-wide association studies to screen for population-based cancer susceptibility loci, this intergenic remote HRE has been identified as a susceptibility locus for renal cell carcinoma, regulating CCND1 expression via HIF-2 specifically in VHL-defective renal cancer cells." (PMID 26007655, 2015). "Recently, the functional polymorphisms in Cyclin D1 (CCND1) have been shown the potential influence to risk of renal cell cancer (RCC)." (PMID 29113352, 2017). "Fisetin has been shown to suppress cell proliferation through G2/M-phase cell cycle arrest, the downregulation of cyclin D1, and the upregulation of p21/p27 in renal cell carcinoma (RCC)." (PMID 40002335, 2025). "have found that G6PD facilitates renal cell carcinoma proliferation through a positive feedback loop involving the activation of the G6PD/ROS/p−STAT3/Cyclin D1 axis." (PMID 37601657, 2023). "For example, in renal cell cancer, pontin knockout led to a decreased mRNA of both MYC and Cyclin D1, associated with a decrease of nuclear β-catenin expression." (PMID 32517078, 2020). "Renal cell carcinoma A498 cells treated with 2.5 μM As2O3 for 72 h resulted in a down-regulation of cyclin D1." (PMID 26359868, 2015). "CCND1 is involved in numerous cellular functions (e.g., growth, metabolism, and differentiation) and also functions as a proto-oncogene in renal cell carcinomas." (PMID 23637735, 2013). "For example, in renal cell carcinomas, PEA can inhibit lung metastasis of tumor cells, and down-regulate a series of tumor-related proteins such as cyclin D1, vascular endothelial growth factor receptor-1 (VEGFR1), etc.." (PMID 37637156, 2023). "For RCC, CCND1 has been discovered as a biomarker for clear cell renal cell carcinoma." (PMID 33627123, 2021). "It has been shown that both PPARα pharmacological antagonism and siRNA‐mediated PPARα KD reduce the expression of c‐Myc, cyclin D1 and CDK4 in renal cell carcinoma (RCC) in vitro models." (PMID 30565681, 2019). "Therefore, it is also possible that USF2 also participates in the HIF2α-dependent expression of PHD3, OCT-4, NDRG1, TGFA, GLUT1, CCND1 and SLC7A5 in renal cell carcinoma." (PMID 33321829, 2020). "Interestingly, the CCND1 gene, which has been found up regulated in clear cell chondrosarcomas, has also been reported as a pVHL-dependent HIF target gene in renal cell carcinoma." (PMID 31673890, 2020). "CCND1 protein expression was examined in protein extracts from a panel of renal cell carcinomas (RCCs) (T) of either the clear cell (CC-RCC) or papillary type and compared to CCND1 protein expression in adjacent macroscopically normal tissue (N) from the same patient." (PMID 15026807, 2004). "In renal cell carcinoma, MAPK activation correlated with MAPK kinase activation and Raf-1 activation, while for hepatocarcinomas a relationship was reported between ERK1/2 activation and expression of the transcription factor c-Fos and cyclin D1." (PMID 15280923, 2004). "In renal cell carcinoma, cyclin A is a powerful and independent prognostic factor in all clinical stages of the disease, whereas cyclin D1 and p21(waf1/cip1) have no prognostic value." (PMID 10471053, 1999). "In renal cell carcinoma (RCC), tumor-derived exosomal circ-PPKCI increases tumor cell proliferation via the miR-545-3p/CCND1 signaling pathway." (PMID 37525158, 2023). "In renal cell cancer, CCND1 was absent in normal kidney samples but overexpressed in RCC." (PMID 27583477, 2016). "The relationship between CCND1 and renal cell carcinoma has not yet been fully determined, but its tendency to increase expression in the early stages of renal cell carcinoma may serve as an indicator for early diagnosis of renal cell carcinoma." (PMID 31850854, 2019).